TNF (tumor necrosis factor)
Diseases named in the same sentence as TNF in open-access papers (continued):
Sharing a sentence is not in itself a finding about the gene and the disease.
colitis (continued). "In addition, colitis mice that were administered BMVs from normal and DSS-miR-200b-3p feces showed reduced levels of inflammation-related parameters in the serum and colon, including decreased IL-6 and TNF-α levels and increased IL-10 levels." (PMID 36176029, 2022). "Of note, we have observed a discrepancy in genetic and pharmacological TNF inhibition on IL-22BP production: blockade of T cell-derived TNF during established colitis induced tissue repair via the IL-22/IL-22BP axis, while genetic depletion of TNF in T cells did not affect IL-22BP." (PMID 35383266, 2022). "In DSS colitis model, the levels of pro-inflammatory cytokine, TNF-α was tremendously (P < 0.001) increased in the colitis group (0.261 ± 0.06 pg/ml/mg protein) against the non-colitis group (0.052 ± 0.01 pg/ml/mg protein), strongly indicating DSS mediated inflammatory response." (PMID 34539597, 2021). "However, the bacteria Lactobacillus enriched in the colitis group had a strong negative correlation with the colonic level of TNF-α (R < − 0.59, P < 0.05)." (PMID 34493333, 2021). "Research in murine models of dextran sulphate sodium (DSS)-induced colitis showed that administration of cocoa FGM-derived polyphenols led to significant abrogation of intestinal length reduction, accompanied by a significant drop of TNF-α and IL-1β in the inflamed colon." (PMID 33806061, 2021). "Interestingly, an initial injection of analogue 5, but not of anti-TNFα antibody, only during the first peak of colitis conferred significant resistance to disease recurrence during a second cycle of DSS administration." (PMID 33767180, 2021). "This review addresses selected laboratory biomarkers (including ANCA, chitinase 3-like 1, S100A12/RAGE, calprotectin, and TNF/TNFR2), which are identified by utilizing two well-accepted animal models of colitis, dextran sodium sulfate-induced and T cell receptor alpha knockout colitis models." (PMID 33573291, 2021). "LTA reduced the lipopolysaccharide (LPS)-mediated histological damage, decreased the level of TNF-α, IFN-γ, IL-6 and IL-1β and enhanced the intestinal permeability by increasing the expression of certain tight junction proteins in LPS-induced murine model of colitis." (PMID 33219923, 2021). "In addition, magnolol restrained the expression of TNF-α, IL-1β, and IL-12 via the regulation of NF-κB and peroxisome proliferator-activated receptor-gamma (PPAR-gamma) pathways and played protective effects on DSS-induced colitis." (PMID 34159200, 2021). "Therefore, we analyzed the secreted pro-inflammatory cytokines in colonic tissue of mice and found that the DSS-induced increased secretion of IL-6, IL-1β, and TNF-α was significantly reduced by saffron (20 mg/kg), reducing the severity of the DSS-induced colitis." (PMID 34199466, 2021). "Additionally, in intestinal epithelial cells of colitis, TNF-α/ARRB1-dependent signaling in hematopoietic and non-hematopoietic cells differentially regulates colitis pathogenesis in modulating MAPK pathways." (PMID 33753990, 2021). "However, oral gavage of NK210 or NK219 suppressed LPS-induced colitis: they decreased myeloperoxidase activity, NF-κB+/CD11c+ cell population, and IFN-γ to IL-10 and TNF-α to IL-10 expression ratios in the colon while colon shortening was not significantly increased." (PMID 34667205, 2021). "For colitis, mainly EPS and extracellular vesicles, but also lactate, they have been described to have an anti-inflammatory role against a variety of acute inflammatory insults: DSS (dextran sulfate sodium), TNFα, FliC (flagellin), IL-1β, and TNBS (2,4,6-trinitrobenzene sulfonic acid)." (PMID 34745425, 2021). "We demonstrated that both extracts, when administered orally, could reduce the elevated levels of pro-inflammatory cytokines, including TNF-α, IL-1β, and IL-6, in the Dextran Sodium Sulfate (DSS) colitis mouse model and effectively ameliorated the experimental colitis." (PMID 34940701, 2021).
colitis (continued). "IL-10-secreting neutrophils might induce immunosuppression under certain conditions and aggravate colitis by enhancing colonic bacterial invasion, suggesting a potentially important role for TRAF2-mediated TNF-α signaling in regulating IL-10-mediated colonic homeostasis." (PMID 34956195, 2021). "Specifically, the histone demethylase, jumonji domain-containing protein 2D (JMJD2D), which is induced by TNF-α/NF-κB signalling, can act as an upstream signal of Hh to induce increased Hh signalling, thereby protecting mice from dextran sodium sulphate (DSS)-induced colitis." (PMID 34702800, 2021). "In a rat colitis model, the potential therapeutic anti-inflammatory/antioxidant activity of mango involves inhibition of cyclooxygenase (COX-1 and COX-2) by proanthocyanidin, inhibition via tumor necrosis factor (TNF)-α, IGF-1/mTOR pathway, as well as PI3K/Akt/mTOR pathway." (PMID 33167456, 2020). "Another study of experimental colitis in rats treated with APS found that A high dose of APS (200 mg/kg) or dexamethasone could markedly downregulate the expression of IL1β and TNF-α and upregulate the protein expression of nuclear factors of activated T cells 4 mRNA." (PMID 32265719, 2020). "In particular, it was reported in murine DSS colitis that the activation of A3AR, expressed in colonic epithelia, exerts anti-inflammatory activity through the inhibition of the pro-inflammatory cytokine TNF and IL-1β via the inhibition of the NF-κB signaling pathways." (PMID 32575844, 2020). "The observed profile of cytokine modulation (IL-6/ TNF-α, IL-8) and inhibition of release of NO and 5-LOX may contribute to the in vivo effects demonstrated by indane dimers and PH46A in murine models of colitis." (PMID 32301120, 2020). "Supplementation of taxifolin significantly inhibited the secretions of tumor necrosis factor-α, interleukin (IL)-1β, and IL-6 and significantly increased the secretions of IL-10, secretory immunoglobulin A, superoxide dismutase, and immunoglobulins (IgA, IgG, and IgM) in DSS-induced colitis mice." (PMID 33664740, 2020). "Soybean-derived dipeptides and tripeptides decreased the colonic expressions of proinflammatory IFNG, IL-1B, IL-12B, TNF, and IL-17A and MPO activity and increased Foxp3 expression and CD4+CD25+ T cells; therefore, the colon and ileum inflammation of piglets with DSS-induced colitis was attenuated." (PMID 32963495, 2020). "To demonstrate whether IFN-γ or TNF-α priming can grant TMSCs beneficial preventive and therapeutic potency in vivo, we utilized a DSS-induced murine colitis model that T cell- and macrophage-mediated immune responses play a critical role in the disease pathogenesis." (PMID 33276479, 2020). "We found that the levels of TNF-α, IL-1β, and IL-6 were significantly increased, however, the production of IL-12 was remarkably decreased in LXN−/− mice during DSS-induced colitis, suggesting TNF-α, IL-1β, IL-6 and IL-12 involved in DSS-induced colitis in LXN−/− mice." (PMID 32555320, 2020). "In conclusion, resistant maltodextrin could increase the level of short-chain fatty acids in the colon, and butyric acid played an anti-inflammatory role to inhibit proinflammatory cytokines (IFN-γ and TNF-α), which finally presented as the intestinal morphological repair of DSS-induced colitis." (PMID 33015180, 2020). "Indeed, GSK343 administration led to a profound decrease in the levels of pro-inflammatory cytokines, including IL-6 and IL-1β, whereas the levels of TNF-α and IL-17A remained unaffected, indicating that GSK343 treatment reduces the inflammatory response during DSS-induced colitis." (PMID 31160593, 2019). "PXR activation by PCN is protective against DSS-induced colitis due to the activation of phase II enzymes and cellular efflux transporters, such as GSTa1, MDR1a, and MRP2, which alleviates the expression of the proinflammatory cytokines IL-6, TNF-α, ΜCP-1, and IL-1β." (PMID 30804707, 2019).
colitis (continued). "Serum interleukin (IL)-12 concentration correlated with colitis activity but IL-1β and TNF did not." (PMID 31172380, 2019). "Moreover, it was previously reported that TNF-α, IL-6, and MCP-1 mRNA expression increased in mesenteric fat depots, 2 days after the induction of Trinitrobenzene Sulfonic Acid (TNBS)-Induced Colitis in mice, which could be dependent on the NF-κB pathway." (PMID 31211796, 2019). "Therefore, a rat model of colitis was established in this paper and the changes of NF-κB, TLR4 and TNF-α during the treatment with probiotic VSL#3 were explored, in order to prove the mechanism of action of probiotic VSL#3 in the treatment of colitis and provide clinical references." (PMID 31497551, 2019). "Also, significant reductions of the TNF levels in the animals treated with BmooMP-alpha-I in all doses tested were observed, with a reduction average of 38.9% compared to that of the DSS-inducted colitis group." (PMID 31467484, 2019). "As evidenced in a DSS-induced colitis model, IPA protects lipopolysaccharide (LPS)-challenged mice by activating AhR to promote interleukin-10 (IL-10, an anti-inflammatory cytokine) production while suppressing gene expression of TNF-α, a proinflammatory cytokine." (PMID 30691236, 2019). "Furthermore, ASA treatment was not able to decrease the level of TNF-α and IL-17 in colitis mice serum after inhibition of FasL in iGMSCs." (PMID 31796122, 2019). "In case of an acute severe colitis, a medical emergency in children, defined by a high clinical disease activity score (paediatric ulcerative colitis activity index; PUCAI) ≥65, IFX is recommended as second-line medical therapy for anti-TNF naïve children failing intravenous corticosteroids." (PMID 31126015, 2019). "GH decreased the protein and mRNA levels of IL-6 and TNF-α, iNOS and COX-2 mRNA expression, the activation of NF-κB and MAPK pathways, the phosphorylation of AMPKα and PRAS40, histological damage, and infiltration of macrophages in the colons of mice with DSS-induced colitis." (PMID 32009962, 2019). "Notably, experimental colitis did not increase IL-1ß expression in the mPFC, despite increasing TNF-α and CD86 expression." (PMID 31882991, 2019). "Cytokines such as TNF-α and IL6 were highly expressed in humans with IBD and experimental models of IBD, and interventions to block their accumulation could protect against colitis." (PMID 31632373, 2019). "Moreover, there was no significant discernment in TNF-α levels between colitis rats treated with prednisolone or thymol." (PMID 31763213, 2019). "However, recent data suggests that neither infliximab binds TNFα, nor TNFα is necessary for colitis in TNFα−/− mice contradicting current admitted mechanism for infliximab action on mouse model based on TNFα neutralization." (PMID 31238939, 2019). "Also, serum levels of both the proinflammatory cytokine TNF-α and anti-inflammatory IL-10 were higher (1.3-fold, P = 0.05) in ceftriaxone-pretreated rats vs. colitis group without antibiotic treatment." (PMID 31437166, 2019). "Thus, the DSS-induced colitis resulted in an increase in MPO, INF-γ, IL6, IL1-β, TNF-α, and IL10." (PMID 28528363, 2018). "Using a model of DSS-induced colitis, there is evidence to the antioxidant and anti-inflammatory abilities of ZnOnps in suppressing ROS and malondialdehyde (MDA) production, increasing GSH levels, and suppressing proinflammatory cytokines IL-1β and TNF-α and myeloperoxidase." (PMID 30258848, 2018). "In addition, blood monocytes produced significantly greater IL-1β but not TNF during DSS colitis when stimulated with LPS, suggesting this pro-inflammatory potential is enhanced even before leaving the blood." (PMID 30542349, 2018). "Interestingly, even rats with colitis alone, which received no midbrain injection of LPS, showed increased levels of TNF-α, iNOS, and IL-6 mRNA in the midbrain." (PMID 30441866, 2018).
colitis (continued). "PF2405, a standardized fraction of S. baicalensis, can significantly inhibit TNF-α induced COX-2 expression through JNK1/2 dephosphorylation and p38 MAPK in HT-29 cells and reduced the expression of proinflammatory cytokines and COX-2 in TNBS-induced colitis in female C57BL/6 mice." (PMID 28690663, 2017). "IL-6 also showed trend of increase in colitis, while TNF-α levels did not change." (PMID 28955126, 2017). "Likewise, treatment with fraxinellone, a natural lactone endowed with immunosuppressive activity, significantly reduced weight loss, diarrhea and colonic macroscopic damage, as well as myeloperoxidase, alkaline phosphatase, and colonic TNF, IL-1β, IL-6, and IL-18 levels in DSS-induced colitis mice." (PMID 28179906, 2017). "However, after DSS-induced colitis, the levels of MIP-2 (0.219±0.020 versus 0.133±0.011 ng ml−1, 95% confidence interval, 3 replicates) and tumour necrosis factor-α (TNF-α) (0.163±0.011 versus 0.118±0.009 ng ml−1) were dramatically increased in the colon of ACF7 cKO mice compared with WT organ." (PMID 28541346, 2017). "Macroscopic and microscopic colitis in sedentary SD mice was accompanied by a significant fall in CBF, some increase in colonic tissue weight and a significant increase in the plasma levels of tumour necrosis factor-alpha (TNF-α), IL-6, monocyte chemotactic protein 1 (MCP-1) and IL-13 (p < 0.05)." (PMID 28425943, 2017). "The glycyrrhizic acid could significantly reduce TNF-α and IL-1β levels in TNBS-induced colitis rats, and in vitro experiments indicated that glycyrrhizic acid could inhibit IL-6 and elevate IL-10 production in LPS-activated macrophages and significantly inhibit lymphocytes proliferation." (PMID 28690663, 2017). "The results showed that GW9662 itself did not affect the disease symptoms of mice with colitis, but significantly weakened bergenin-mediated regulation of levels of IL-6, TNF-α, acetylated NF-κB-p65, SIRT1 and nuclear translocation of NF-κB-p65 in colons, and consequent anti-colitis effect." (PMID 29375382, 2017). "As colon biopsies and sera from IBD patients have increased concentrations of TNF-α and IL-6, the suppressive effect of GpS on TNF-α and IL-6 production in the colons of colitis mice may also indicate the potential inhibitory effect of GpS on NF-κB and STAT3 signaling." (PMID 29152090, 2017). "IBD98-M may reduce injuries during colitis through inhibiting COX-2 and TNF-α expression." (PMID 28556814, 2017). "Thus, inhibition of the TNF-α-mediated activation of the NF-κB and MAPK pathways might represent important mechanisms by which H-SN1 is able to alleviate colitis in the DSS model." (PMID 27158082, 2016). "In rats without induction of colitis, intragastric administration of Mutaflor or rifaximin for 7 days failed to affect mucosal concentration of interleukin-1β (IL-1β) or Tumor Necrosis Factor-α (TNF-α) in the colon (resp)." (PMID 27433160, 2016). "Due to the genetic absence of TNF in both T/I mice that developed colitis and their T/I-het littermates that did not, use of these mouse strains allowed us to assess factors other than TNF that may affect food consumption and growth." (PMID 27045690, 2016). "That no significant increase in epithelial permeability was seen after DSS treatment in Arhgap17-deficient mice despite a dramatic TNF induction indicates that TNF-mediated disruption of intestinal TJ barriers is not an initial event of the DSS-induced colitis in these mice." (PMID 27229483, 2016). "Consistent with this, neutralization of membrane-bound TNF has been shown to induce T cell apoptosis and was effective in suppressing experimental colitis in mice, whereas activation of TNFR2 (which is induced by membrane-bound but not soluble TNF) on T cells was found to aggravate colitis activity." (PMID 27347881, 2016).
colitis (continued). "In rats without colitis, administration of ghrelin for six or 13 days after rectal enema with saline had no impact on the concentration of interleukin-1β (IL-1β) or tumor necrosis factor-α (TNF-α) in the mucosa of the colon." (PMID 27598133, 2016). "In addition, it has been also shown that infliximab, an anti-TNF-alpha antibody, could prevent CAC in DSS-induced colitis, an effect which was accompanied by the reduction of MMP-9 and MMP-11 levels." (PMID 25948887, 2015). "We believe that these findings support the accepted theory that TNF is a master regulator and is critical in acute inflammatory responses and that the lack of TNF production or signaling resulted in decreased colitis, which otherwise would likely have proceeded uninhibitedly." (PMID 25775453, 2015). "We hypothesized that TNBS colitis would result in HIF-1α activation, particularly within the epithelium, resulting in increased expression of pro-inflammatory cytokines such as IL-1β and TNF-α, and higher levels of iNOS." (PMID 25926972, 2015). "Recent work has demonstrated that membrane-bound TNF, rather than soluble TNF, acts on intestinal inflammation and that neutralization of membrane-bound TNF with specific antibody such as IFX could induce T cell apoptosis and suppress experimental colitis in mice." (PMID 26572590, 2015). "Lamina propria macrophages of EPRAP-deficient mice exhibited marked increases in the mRNAs corresponding to TNF-α, IL-1β, IL-6, CXCL1, and MCP-1 relative to those of WT mice, indicating that EPRAP contributes critically to inhibiting macrophage activation and colonic inflammation." (PMID 26439841, 2015). "LPMCs isolated from OPN/IL-10 DKO mice expressed higher levels of TNF-α and IL-12p40 than those from IL-10 KO mice at 4 weeks of age, suggesting that intestinal macrophages are highly activated in OPN/IL-10 DKO mice at an early stage of colitis compared to IL-10 KO mice." (PMID 26274807, 2015). "In this study, the DAI and HI scores, MPO activity in colonic tissues, as well as the MDA, TNF-α, IL-1β, and IL-6 levels, were simultaneously increased in TNBS-induced colitis rats with Hcy injection, indicating that Hcy can aggravate the oxidative and inflammatory damage in rats with colitis." (PMID 24787389, 2014). "Indeed, administration of infliximab restored the proper function of intestinal epithelium in CD patients and prevented TNF-induced rearrangement of tight junction proteins (notably, occludin and zonula occludens-1) in dinitrobenzene sulfonic acid- (DNBS-) induced colitis in mice." (PMID 25045210, 2014). "It has been reported that DSS can develop colitis in the absence of TNF-α." (PMID 24586391, 2014). "This DSS colitis switches from a Th1-Th17-mediated acute inflammation with increased levels of TNF-α, IL-6 and IL-17, to a predominant Th2-mediated inflammatory response that shows a decrease in TNF-α, IL-6 and IL-17 while increasing levels of anti-inflammatory cytokines IL-4 and IL-10." (PMID 25106058, 2014). "Given that activated neutrophils, monocytes and macrophages up-regulated the production of pro-inflammatory mediators such as TNF-α and IL-6 in experimental colitis, we further investigated whether chronic VNS could decrease the levels and expression of TNF-α and IL-6." (PMID 23936328, 2013). "In addition, Liu and Wang reported that TNF-α that is released from macrophages during the first stage of inflammation plays a vital role in 2,4,6-trinitrobenzenesulfonic acid (TNBS)—induced colitis and is identically the key controller of the inflammatory flow in this IBD model." (PMID 23783459, 2013). "Notably, mice lacking the CLR Dectin-1 also display higher TNF-α levels in the colon after induction of colitis." (PMID 23882266, 2013).